BAP1 (BRCA1 associated deubiquitinase 1)
Diseases named in the same sentence as BAP1 in open-access papers (continued):
Sharing a sentence is not in itself a finding about the gene and the disease.
cancer (continued). "However, PanCancer supports our finding of lower BAP1 expression in benign versus cancer tissues and tissue-based expression data of weak BAP1 expression linked with worse clinical outcomes." (PMID 40136571, 2025). "Low BAP1 expression promotes genomic instability by failing to regulate DNA repair pathways or by altering the expression of other tumor suppressor genes, contributing to an aggressive cancer phenotype." (PMID 40136571, 2025). "It is evident from the data that genes such as VHL, TTN, BAP1, PBRM1, and SETD2 are consistently identified as the most frequently mutated genes in KIRC, underscoring their potential importance as key drivers of tumorigenesis in this specific cancer subtype." (PMID 40649942, 2025). "It has been demonstrated that BAP1 regulates context-dependent transcriptional programs in different cancer types and may play opposing roles in different tumorigenesis." (PMID 39817454, 2025). "Previous studies indicated that BAP1 might inhibit cancer cell growth by interacting with one or more partner proteins, including YY1, RBBP7, HCF-1, H2A, ASXL1/2, and FoxK1/K2." (PMID 40688406, 2025). "It is therefore possible indeed that malfunctions in BAP1, even though leading to cancer progression, may prevent the formation of CSCs, thereby reducing the aggressiveness of the cancerous cells." (PMID 38459714, 2024). "Interestingly, E7820-mediated double-strand breaks in DNA were increased in tumors with BRCA2 dysfunction, and knockdown of BRCA1/2 transcripts or knockout of ATM, ATR, or BAP1 sensitized cancer cells to E7820." (PMID 38789724, 2024). "In cancer cells expressing a BAP1 mutant defective in ASXL2 binding, PR-DUB activity is disrupted, suggesting that BAP1 C-terminal domain mutations may contribute to cancer development." (PMID 38791157, 2024). "Especially, the presence of co-occurring mutations or epigenetic changes, such as mutations in BAP1, can influence whether a GNAQ or GNA11 mutation leads to a benign lesion or a malignant tumor." (PMID 39518110, 2024). "Further studies can investigate whether Med1 phosphorylation affects the binding ability of BAP1 protein and the role in cancer cell growth and metastasis capacity." (PMID 38708315, 2024). "Of the cancer types represented in TCGA, 21/33 (63.6%) have at least one BAP1 mutant sample." (PMID 39554490, 2024). "Clinical studies have shown that the BAP1 gene is lost or inactivated in various cancers." (PMID 39336594, 2024). "However, in the future, the results of this study will contribute to various research fields, such as the mechanism of regulating the expression of target genes by the binding of Med1 and BAP1 and the growth and metastasis of cancer by Med1 and BAP1." (PMID 38708315, 2024). "The relationship between BAP1 and Med1 expression may be context-dependent and could differ in other cancer cell lines or types." (PMID 38708315, 2024). "Thus, Med1 and BAP1 can serve as biomarkers for cancer development or metastasis, and targeting agents serve as potential gene therapeutic targets in various cancers." (PMID 38708315, 2024). "In addition, an examination of the interaction between Med1 and BAP1 proteins showed that Med1 and BAP1 proteins are binding and are involved in the development and metastasis of cancer." (PMID 38708315, 2024). "Larger sequencing studies in unselected cancer individuals show that BAP1-TPDS may be more common than previously thought, but the limited number of families reported to date still limits our understanding of the phenotypic spectrum." (PMID 38824259, 2024). "BAP1’s involvement in cancer immunity was initially underreported." (PMID 39350280, 2024). "Notably, genes identified in these metastatic patients—BAP1, BRAF, and EGFR—have been previously reported in association with cancer metastasis." (PMID 38893126, 2024). "Sex-biased genes include well-known drivers of cancer such as b-catenin and BAP1." (PMID 39713142, 2024).
cancer (continued). "The lower frequency of multipolar spindles in mitosis compared to amplified centrosomes in interphase in response to BAP1 or BRCA1 depletion may be explained by the ability of cancer cells to cluster amplified centrosomes to form pseudo-bipolar spindles." (PMID 36550359, 2023). "Increasing implementation of large solid tumour panel tests and paired whole genome sequencing means that BAP1 testing may also be undertaken in patients with cancer outside the known spectrum of BAP1-TPDS." (PMID 37607989, 2023). "When SLC7A11 is inhibited, BAP1 triggers ferroptosis to partially inhibit cancer progression." (PMID 37210575, 2023). "Mechanistically, BAP1 loss has been proposed to act by driving dedifferentiation and stem‐like characteristics associated with early cancer rather than tumorigenicity." (PMID 36740402, 2023). "Clinically, loss of BAP1 and CDKN2A expression can be useful ancillary markers for differentiating between cancer and reactive mesothelial cell proliferations and are required for diagnosis of the recently established pathological entity malignant mesothelioma in situ (MMIS)." (PMID 38015374, 2023). "Though apparently distant (not directly linked), understanding the multifaceted involvement of UCH-L1 and BAP1 in cancer and NDD could be of importance." (PMID 36923654, 2023). "Our study therefore provides an additional example of the oncogenic role of BAP1 in common cancers." (PMID 36754982, 2023). "People with mutations that inactivate BAP1 function always develop at least one and often multiple cancers, but specifically how BAP1 mutations cause cancer is not well understood." (PMID 37009801, 2023). "In addition to GEMMs, modification of human cell lines by reexpression or genetic deletion of BAP1 can provide useful insights, although to date cancer cell lines with heterogenous genetic alterations have been employed." (PMID 36669126, 2023). "To explore whether the relationship between ASS1 and BAP1 was a general feature of cancer, we examined TCGA pan-cancer datasets." (PMID 36669126, 2023). "Interestingly, we found that they comprised nearly a quarter of the entire group of SPCs; among them, the majority were cancers potentially related to BAP1-TPDS." (PMID 36980631, 2023). "PARP inhibition might have exerted an effect on uncharacterized BAP1-irrelevant DNA repair pathways on which cancer cells rely for survival." (PMID 37009801, 2023). "If a germline BAP1 mutation is identified, a thorough cancer history should be performed, and family genetic counseling should be considered to rule out other cancers." (PMID 37010677, 2023). "SETD2, BAP1, and MTOR possessed higher mutation frequencies in the high-risk group than in the low-risk group implying that these three cancer-driven mutations may promote the progression of KIRC." (PMID 37342680, 2022). "This miRNA signature was considered an independent prognostic factor for BAP1 wild-type cancer." (PMID 36012262, 2022). "All these findings are contradictory to other types of cancer, and indicating that BAP1 may play different roles in development of HCC." (PMID 34976173, 2022). "Notably, two members of the ubiquitin C-terminal hydrolases (UCHs) family, BRCA1-associated protein-1 (BAP1) and UCH-L3 have been implicated in the survival rate of this particular cancer." (PMID 36009801, 2022). "Unlike the LOF BAP1 mutations observed in cancer, these truncating ASXL1 mutations result in hyper-deubiquitination activity for PR-DUB complexes." (PMID 36105358, 2022). "Since they arise during the first two decades of life and tend to increase in number with age, their detection can be useful for early cancer diagnosis as they help identify BAP1 PV carriers several years before the development of more aggressive tumors belonging to the BAP1-TPDS spectrum." (PMID 35885614, 2022).
cancer (continued). "However, BRCA1-associated protein 1 (BAP1) blocks ubiquitination of histone 2A leading to inhibition of SLC7A11 gene transcription, subsequently, increases lipid peroxidation and promotes cancer cell ferroptosis." (PMID 36289191, 2022). "Given the widespread functional role of BAP1 in cellular pathways implicated in cancer, it is not surprising that the BAP1 gene is altered in a variety of tumors." (PMID 34976173, 2022). "However, emerging studies have uncovered the dual roles of BAP1 or the BAP1 complex and how this can impact tumorigenesis in different human cancers." (PMID 35194152, 2022). "Importantly, we show that certain tumors present in PV carriers retain a wt BAP1 allele, which implies a sporadic origin of these tumors or a functional role of heterozygous BAP1 in cancer development." (PMID 35885614, 2022). "The mutation rate of BAP1 in HCC was 5.49%, higher than most of other cancers." (PMID 34976173, 2022). "Although she had an extensive personal history of cancer suggestive of cancer predisposition, her clinical phenotype and family history would not have predicted either BAP1 or RECQL4 mutations prior to testing." (PMID 33541411, 2021). "More importantly, large‐scale clinical relevance analyses showed that BAP1 was positively related to PTEN at the protein level in many kinds of human cancers, suggesting that the positive correlation between BAP1 and PTEN may be ubiquitous." (PMID 33155366, 2021). "Furthermore, deep mutational profiling showed that BAP1 is inactivated by either copy number or point mutations in about 57% of MPM cases, representing the most frequent alteration in this type of cancer." (PMID 34199544, 2021). "The daughter tested positive for a pathogenic BAP1 variant (NM_004656.4:c.1777C>T, (p.Gln593*) with no other cancer susceptibility loci found mutated (CancerNext-Expanded, Ambry Genetics)." (PMID 34504799, 2021). "Molecular studies have revealed the compensatory mechanisms involved in cancer cells with the loss of BAP1 expression and lack of accelerated cell death." (PMID 33919439, 2021). "In recent years, BAP1 has been studied extensively in various cancers." (PMID 33529461, 2021). "Nonsense mutations that are predicted to be pathogenic and cancer-related in ClinVar are in RB1 in UM-MCC9 (rs794727481) and UM-MCC34 (rs121913304), in BAP1 in UM-MCC32 (chr3.52437267.G > A), and in the tumor-suppressor gene CHEK2 in MKL-1 (chr22.29091725.C > T)." (PMID 33562873, 2021). "The potential role of H2Aub and cancer is also provided by the DUB BAP1 and its co-factors ASXLs." (PMID 33230107, 2020). "Subsequent research has not been able to name an unequivocal cancer driver gene, even though several candidates have been suggested, including BAP1 and MIR135A45,46, which were detected as eQTL variants in our target gene analysis." (PMID 32964118, 2020). "Others, including BAP1 and iron, induce ferroptosis to kill cancer cells." (PMID 33665167, 2020). "These patients also have strong family history of BAP1-related cancers." (PMID 33240524, 2020). "For an appropriate clinical management of BAP1-TPDS patients, we suggested a surveillance plan based on preliminary proposals, informing the patients about the risk of additional cancers associated with the syndrome and about the uncertainty of the efficacy of surveillance for some of these cancers." (PMID 32325837, 2020). "BAP1, or BRCA1-associated protein, is a nuclear-localized DUB and may be the most commonly mutated DUB in cancers." (PMID 32549302, 2020). "BAP1 has been found to play an essential role in cancer cell death via inducing ferroptosis." (PMID 33665167, 2020). "In cancer cells, BAP1 removes monoubiquitin from ubiquitinated H2A at lysine 119 (H2Aub) on the SLC7A11 promoter to suppress its expression in cells treated with erastin but not RSL3, and this effect does not require the transcription factors NRF2 and activating transcription factor 4 (ATF4)." (PMID 33294126, 2020).
cancer (continued). "The occurrence of mutation rates in UCHs also suggests that BAP1 and UCH-L5 may play a more dominant role in cancers than UCH-L1 and UCH-L3." (PMID 32486284, 2020). "Fortunately, there are less significantly mutated genes in ccRCCs compared with other cancers; the top four most commonly mutated genes are von Hippel-Lindau (VHL) tumor suppressor gene, polybromo-1 (PBRM1), BRCA1-associated protein 1 (BAP1), and SET domain containing 2 (SETD2)." (PMID 32185138, 2020). "BAP1 was also reported to modulate cancer cell sensitivity to radiotherapy and the molecular inhibitors including PARP (olaparib) or histone deacetylase inhibitors (panobinostat), which may become potential therapeutic strategies." (PMID 33585209, 2020). "Furthermore, both xenograft model studies and human population studies have confirmed that BAP1 shows its anti-cancer effect by inducing ferroptosis." (PMID 33665167, 2020). "Nonetheless, as the roles of BAP1in the context of cancer progression are diverse and context-dependent, it isimperative to find a specific substrate of BAP1—that is involved in the promotion ofprostate cancer—to precisely characterize the functional mechanisms of BAP1." (PMID 32422649, 2020). "The c.944A>C, p.Glu315Ala variant in BAP1 in family 5001 has not been reported in families with BAP1-associated cancers but has a population frequency of 0.016%." (PMID 31034483, 2019). "BAP1 also plays a prognostic role in other cancers such as RCC and cholangiocarcinoma." (PMID 30716094, 2019). "Although BAP1 is conceptually a driver gene in UM, it might contribute through its interaction partners and its regulatory miRNA network to various aspects of cancer." (PMID 31635116, 2019). "Herein, we suggest that although BAP1 is conceptually a driver gene in UM, it might contribute through its interaction partners and its regulatory miRNA network to various aspects of cancer." (PMID 31635116, 2019). "BAP1 inactivation (mutation or loss) is a rare event in most cancer types and would be unlikely to be a universal predictor of liver metastasis." (PMID 31748560, 2019). "Furthermore, we determined the distinctive gene expression spectra of the BAP1 gene in different types of cancer." (PMID 31635116, 2019). "This suggests that although BAP1 is conceptually a driver gene in UM, it might contribute globally to the cancer genome." (PMID 31635116, 2019). "Aside from malignant tumors, BAP1-inactivated nevi (BIN), previously called melanocytic BAP1-mutated atypical intradermal tumors (MBAITs) or BAP-oma, commonly occur in patients with BAP1-TPDS." (PMID 31382694, 2019). "The mammalian homologs of these proteins (BAP1 and ASXL1/2/3, respectively), are frequently mutated in various cancer types, yet their precise functions remain unclear." (PMID 30664650, 2019). "That BAP1 expression lacks prognostic impact in cancers with identical quantitative Gleason grade demonstrates the statistical power of the quantitative Gleason grading system, however, it is not universally applied and does not solve all issues of interobserver variability in PCa grading." (PMID 31903168, 2019).
cancer (continued). "Nuclear BAP1 expression was associated withTMPRSS2:ERG rearrangement and ERG expression: Strong BAP1 positivity increased from 12-14% in 5,415 ERG-negative cancers (by IHC or FISH) to 30-32% in 4,217 ERG-positive cancers (p<0.0001 each)." (PMID 31903168, 2019). "Cancer cells that harbored mutations in the PHD domain of MLL3 or lacked BAP1 showed reduced recruitment of UTX/KDM6A to gene enhancers, with no reduction in the levels of the repressive H3K27me3 mark." (PMID 31221981, 2019). "Future work to analyze BAP1 expression in other cancers will be performed." (PMID 30716094, 2019). "In 15,857 cancers, BAP1 staining was weak in 3.3%, moderate in 41.6% and strong in 17.4%." (PMID 31903168, 2019). "Both ZFHX3 and BAP1 are tumor suppressor genes, their decreased expression may promote the cancer development." (PMID 30107644, 2018). "The aim of this study was to examine BAP1 involvement in canine cancers." (PMID 30060843, 2018). "The functional role of BAP1 down-regulation in cancer cells remains controversial." (PMID 30395583, 2018). "Our findings might have important implications for BAP1 to play a key role in the regulation of cell death in cancer cells, and the expression of BAP1 could have prognostic implications in predicting a good prognosis in cancer patients." (PMID 29686263, 2018). "To validate our hypothesis, we decided to examine the ISGF3 protein levels in ccRCC cancer cells with IHC and correlate their protein levels with the protein levels of BAP1, PBRM1, and SETD2." (PMID 30355451, 2018). "Because ferroptosis and apoptosis are two distinct programs in BAP1-mediated cell death, it will be worth to investigate whether these processes act in concert or independently during cancer development." (PMID 30455474, 2018). "Excluding those 3 families, there is an estimated 2-fold increased risk of a BAP1-associated cancer but this is no longer statistically significant (P = 0.43, data not shown)." (PMID 28062663, 2017). "While mutations in BAP1 and PBRM1 have been shown to be associated with poor cancer-specific survival, the frequency of these mutations (and their clinical relevance) in metastatic ccRCC tumors is unknown." (PMID 28327121, 2017). "However, the roles of BAP1 in the initiation and progression of human cancers remain poorly understood." (PMID 26885612, 2016). "Regulation of BAP1 by miR-31 might explain why the upregulation of miR-31 during lung carcinogenesis can promote cancer progression." (PMID 26885612, 2016). "Also, some of the recently discovered cancer predisposing genes appear to act in accordance with this scenario, such as for instance the MAX, SMARCE1 and BAP1 genes." (PMID 27279102, 2016). "Although the majority of the published studies suggest that the effects of BAP1 in cancer involve a disruption of the epigenetic homeostasis in these tumors, for some researchers, it is not so clear that the antitumor effect of BAP1 is only dependent on H2A deubiquitylation." (PMID 27516771, 2016). "Our findings indicate that BAP1 could be a potential therapeutic target for breast and other cancers." (PMID 26419610, 2015). "Those that do not have disease and are found to be carriers of BAP1 germline mutations can be followed for early cancer detection." (PMID 26683624, 2015). "Amyloidogenicity of BAP1 will inevitably strengthen the prion hypothesis in cancer biology; however a detailed molecular study is necessary to understand its aggregation mechanism." (PMID 26680512, 2015). "The exome sequence data of the person with UMM and wild type BAP1 did not reveal mutations in other known cancer predisposition genes." (PMID 23977234, 2013). "The family described here also had a variety of other cancer types, some of which have been implicated with BAP1 mutation (lung) and some that have not (stomach, neuroendocrine)." (PMID 23977234, 2013). "The odds ratio (OR) of cancer risk in the germline BAP1-mutated cohort versus the non-mutated cohort was 17.39 (95% CI: 6.07-49.83)." (PMID 22935333, 2012).